STEAP2 (STEAP2 metalloreductase)
Description:
Integral membrane protein that functions as a NADPH-dependent ferric-chelate reductase, using NADPH from one side of the membrane to reduce a Fe(3+) chelate that is bound on the other side of the membrane (By similarity). Mediates sequential transmembrane electron transfer from NADPH to FAD and onto heme, and finally to the Fe(3+) chelate (By similarity). Can also reduce Cu(2+) to Cu(1+) (By similarity).
Synonyms: PUMPCn; PCANAP1; STAMP1; IPCA-1; STMP; IPCA1
Tractability: Small molecule: a structure with a bound ligand is known. Antibody: UniProt places it where antibodies can reach, with high confidence; its Gene Ontology location is reachable by antibodies, with high confidence; UniProt predicts a signal peptide or a membrane-spanning region. PROTAC: ubiquitination databases record sites on it.
Gene: Protein-coding gene on chromosome 7 (90,167,590 to 90,238,137, forward strand). Ensembl gene ENSG00000157214.
Subcellular location: Endosome membrane; Cell membrane
Subcellular location (Human Protein Atlas): Vesicles
Gene Ontology:
Molecular function: cupric reductase (NADH) activity; ferric-chelate reductase (NADPH) activity
Biological process: endocytosis; Golgi to plasma membrane transport; regulated exocytosis; response to hormone; copper ion import
Cellular component: cytosol; early endosome; Golgi membrane; plasma membrane; trans-Golgi network transport vesicle; endosome; endosome membrane
Genetic constraint (gnomAD): Loss-of-function variants: 30 observed, 48.4 expected, observed/expected ratio (o/e) 0.62, 90% interval 0.46 to 0.84. The upper end of that interval is the gene's LOEUF score, 0.84, which puts it in group 3 of 6, group 1 being the genes least tolerant of losing a copy. Missense variants: 513 observed, 609.6 expected, observed/expected ratio (o/e) 0.84, 90% interval 0.78 to 0.9. Synonymous variants: 180 observed, 212.5 expected, observed/expected ratio (o/e) 0.85, 90% interval 0.75 to 0.96.
Homologues: Orthologues: chimpanzee STEAP2 (99% identical), pig STEAP2 (98% identical), dog STEAP2 (98% identical), guinea pig STEAP2 (97% identical), mouse Steap2 (97% identical), rat Steap2 (96% identical), macaque STEAP2 (90% identical), rabbit STEAP2 (89% identical), tropical clawed frog steap2 (83% identical), zebrafish steap2 (74% identical). Paralogues in human: STEAP3 (51% identical), STEAP4 (43% identical), STEAP1 (32% identical), STEAP1B (25% identical).
Diseases named in the same sentence as STEAP2 in open-access papers:
STEAP2 is named in the same sentence as 50 diseases in open-access papers, as found by Europe PMC text mining. Sharing a sentence is not in itself a finding about the gene and the disease. The quoted sentences say what the papers report.
prostate carcinoma (35 papers, 2004 to 2025). A carcinoma that arises from epithelial cells of the prostate gland. "Among the STEAP isoforms, STEAP1 and STEAP2 have been identified in EVs associated with prostate cancer." (PMID 40214422, 2025). "STEAP2 is widely expressed in various tissues and cell types, including lungs, kidneys, and immune cells, which suggests the potential roles of STEAP2 in diverse physiological processes beyond its initially identified association with prostate cancer." (PMID 38872435, 2024). "Additionally, proteins such as PD-L1, STEAP1, and STEAP2 are associated with aggressive forms of prostate cancer." (PMID 39766159, 2024). "There is limited information on the relevance of STEAP1 and STEAP2 to the progression and survival of prostate cancer." (PMID 40214422, 2025). "Knockdown of STEAP2 promotes apoptosis in prostate cancer cells, increasing prostate cancer cell proliferation." (PMID 39668818, 2024). "Evidence suggests that STEAP2 is specifically overexpressed in invasive prostate cancer, therefore promoting proliferation, migration, and invasion." (PMID 38830975, 2024). "The opposing roles of STEAP2 in prostate cancer and breast cancer highlight the need for further studies on STEAP2 in various types of cancers." (PMID 38830975, 2024). "Although the biology of STEAP2 regulation and function remains largely unstudied, there is evidence in the literature that STEAP2 increases prostate cancer cell growth and invasion." (PMID 37966111, 2023). "Together, these data underscore the therapeutic tractability of STEAP2 in prostate cancer as well as build confidence in the specificity, potency, and tolerability of this potentially first-in-class CAR-T therapy." (PMID 37966111, 2023). "Collectively, the results of these studies demonstrate that the STEAP2 protein structure, expression profile, and biology are therapeutically tractable and support further evaluation of this target in prostate cancer." (PMID 37966111, 2023). "Six-transmembrane epithelial antigen of prostate-2 (STEAP2) is also over-expressed in prostate cancer and, similar to STEAP1, it is also pro-tumourigenic." (PMID 36831514, 2023). "The production of the STEAP2 should, therefore, be both suppressed in the prostate and where possible, a potent ligand should bind to it to block its role in prostate cancer progression." (PMID 36304279, 2022). "This study aimed at using the STEAP2 prostate cancer biomarker as a target using in silico methods and promising results were achieved." (PMID 36304279, 2022). "And STEAP1 and STEAP2 have previously been reported as potential markers, especially for aggressive prostate cancer." (PMID 35346237, 2022). "While most research regarding the relationships between STEAP2 and cancerous tissues remains at the inception stage, some indicators are clearly available from its defined role in prostatic carcinoma progression." (PMID 36316642, 2022). "The findings from this study give conjecture on the mechanistic role of triptorelin and leuprolide among others if STEAP2 was a target in the treatment of prostate cancer right from the early-stage disease." (PMID 36304279, 2022). "STEAP2 was also reported an overexpressed gene inhibiting apoptosis in several human cancers, especially prostate cancer." (PMID 35313641, 2022). "In contrast, STEAP2 is significantly overexpressed in prostate cancer, and its overexpression promotes the proliferation, migration, and invasion of tumor cells." (PMID 35346237, 2022). "This study aimed to use the STEAP2 protein (prostate cancer–specific biomarker) for the discovery of new targeted therapy." (PMID 36304279, 2022). "proved that reducing the expression of STEAP2 inhibited the proliferation, migration, and invasion in prostate cancer cells." (PMID 34858857, 2021). "Studies on STEAP2 expression in cancers have also mainly focused on prostate cancers, although studies are limited." (PMID 34778263, 2021).
prostate carcinoma (continued). "STEAP2 expression in prostate cancer was found to be significantly higher than that in normal tissues." (PMID 34778263, 2021). "It was reported that STEAP2 was significantly overexpressed in prostate cancer, and the overexpression of STEAP2 promoted the proliferation, migration, and invasion of tumor cells." (PMID 32802887, 2020). "STEAP2 expression has been found to be significantly increased in prostate cancer, and its knockdown reduced the invasive potential of prostate cancer cells." (PMID 32875483, 2020). "STEAP2 is overexpressed in prostate cancer tissues and knockdown of STEAP2 in cell lines inhibits proliferation, cell cycle progression and induces apoptosis through regulation of the MAPK pathway." (PMID 32328462, 2020). "The overexpression of STEAP2 induced the normal prostate cells to gain an ability to migrate and invade while the knockdown of STEAP2 significantly reduced proliferation and migration of prostate cancer cells." (PMID 32149080, 2020). "Knockdown of STEAP2 significantly suppresses the proliferation of prostatic cancer, though current data suggest that this effect occurs probably due to STEAP2 ability to induce enzymatic activity that results in degradation of extracellular matrix." (PMID 30538952, 2018). "In patient tissues, STEAP2 expression was significantly increased in prostate cancer samples and this significantly correlated with Gleason score." (PMID 29674723, 2018). "This study aimed to establish the functional role of STEAP2 in prostate tumourigenesis and evaluate if its knockdown resulted in reduced invasive potential of prostate cancer cells." (PMID 29674723, 2018). "STEAP2 immunohistochemistry was applied to assess the protein expression and localisation according to Gleason score in 164 prostate cancer patients." (PMID 29674723, 2018). "Of these 8 secretion-related genes, 5 genes (FKBP1B, SCIN, SMPD3, STEAP2, and TRIM36) has been associated with prostate cancer and hyperplasia." (PMID 26113971, 2015). "In prostate cancer, STEAP2 expression was associated with ERK activity; phosphorylation of ERK was increased on ectopic expression of STEAP2 and was strongly downregulated in STEAP2 knockdown cells." (PMID 38830975, 2024). "Our studies revealed that six-transmembrane epithelial antigen of prostate-2 (STEAP2) was a prevalent prostate cancer antigen that displayed high, homogeneous cell surface expression across all stages of disease with limited distal normal tissue expression, making it ideal for therapeutic targeting." (PMID 37966111, 2023). "Targeting STEAP2 may, therefore, lead to the development of new anti-prostate cancer therapies in the future with further studies." (PMID 36304279, 2022). "STEAP2 targeting may be studied in the future in the context of developing anti-prostate cancer therapies." (PMID 36304279, 2022). "From the findings of this study, these drugs could treat prostate cancer by binding to and inhibiting the catalytic role of STEAP2 that is responsible for disease progression as seen by the result in this study." (PMID 36304279, 2022). "Our study aimed to identify potential compounds that could be used in the development of anti-prostate cancer drugs that target STEAP2 using molecular docking." (PMID 36304279, 2022). "STEAP2 is highly expressed at all stages of prostate cancer and is androgen independent, a characteristic that is key in managing androgen-dependent and independent/advanced prostate cancer." (PMID 36304279, 2022). "In vitro and in vivo studies show that STEAP2 plays a key role in prostate cancer progression." (PMID 36304279, 2022). "An increased level of STEAP2 in prostate cancer suggests an oncogenic role." (PMID 34778263, 2021). "Similarly, STEAP2 accelerates prostate cancer progression by promoting proliferation, migration, and invasion by regulating the transcriptional profiles of some genes involved in metastasis." (PMID 34858857, 2021).
prostate carcinoma (continued). "The roles of STEAP2 in OvCa may be similar to prostate cancer in which STEAP2 was observed to be upregulated and associated with advanced stage and Gleason score." (PMID 32149080, 2020). "Moreover, recent evidence has demonstrated up-regulation of STEAP2 protein within prostate cancers compared to normal glands." (PMID 32290196, 2020). "Six-transmembrane epithelial antigen of the prostate-2 (STEAP2) expression is increased in prostate cancer when compared to normal prostate, suggesting STEAP2 may drive prostate cancer progression." (PMID 29674723, 2018). "In prostate cancer cells, STEAP2 expression was required for optimal ERK activity; phosphorylation of ERK was strongly downregulated in STEAP2 knockdown cells." (PMID 38830975, 2024). "Prostate cancer has aberrantly upregulated STEAP1, STEAP2, and STEAP4, playing an important oncogene function in tumor malignancy." (PMID 35436987, 2022). "In prostate cancer, STEAP1, STEAP2, and STEAP4 are overexpressed, while STEAP3 expression is downregulated." (PMID 36011027, 2022). "The list of 10 genes again included the well-established prostate cancer markers KLK2, KLK3 (PSA), FOLH1 (PSMA), PSGR (OR51E2), STEAP2, NKX3.1 and Prostein), and also included NCAM2, SPON2 and HOXB13." (PMID 15583692, 2005). "STAMP1 (six transmembrane protein of prostate 1), also known as STEAP2, also overexpressed in prostate cancer, has been located in the trans-Golgi network and shuttles to plasma membranes, which suggest a role in the secretory/endocytic pathways." (PMID 15623366, 2004). "In support of the idea that STEAP2 is a critical driver of prostate cancer, our preclinical studies did not reveal evidence of target loss as a means of resistance to therapy." (PMID 37966111, 2023). "The results provide evidence that the dnTGFβRII-armored STEAP2-targeted CAR-T product, AZD0754, may present a therapeutic option for metastatic castration-resistant prostate cancer." (PMID 37966111, 2023). "STEAP2 has been detected in androgen receptor (AR)-negative and (AR)-sensitive prostate cancer cell lines." (PMID 32290196, 2020).
breast carcinoma (10 papers, 2020 to 2024). "Low expression; Associated with good prognosis; STEAP1 and STEAP2 inhibit the invasion, proliferation, and metastasis of breast cancer by inhibiting EMT." (PMID 39676279, 2024). "al. demonstrates that STEAP2 is downregulated in breast cancer tissues and acts as an anti-oncogene in breast cancer development by suppressing EMT and blocking PI3K/AKT signaling." (PMID 38830975, 2024). "In accordance with our findings, downregulated STEAP2 has been observed in breast cancer and glioblastoma, while STEAP2 downregulation promotes breast cancer cell proliferation and invasion." (PMID 35436987, 2022). "A previous study confirmed STEAP2 was downregulated in breast cancer, and its upregulation inhibited tumor proliferation, invasion, and metastasis by suppressing PI3K-Akt signaling pathway in vitro and in vivo." (PMID 35313641, 2022). "STEAP2 overexpression significantly inhibited proliferation and clonogenesis in breast cancer cells." (PMID 35346237, 2022). "STEAP2 has been reported to inhibit epithelial-to-mesenchymal transition of breast cancer and invasion of papillary thyroid cancer (THCA)." (PMID 36060273, 2022). "Upregulation of STEAP2 can inhibit the invasion and metastasis of breast cancer cells by inhibiting epithelial-mesenchymal transformation by affecting transcription factors." (PMID 35346237, 2022). "The current study also predicted the participation of STEAP1 and STEAP2 in the process of mineral absorption through converting Cu2+ to Cu+ and promoting copper absorption, which may be the underlying mechanism that STEAPs are involved in the development of breast cancers." (PMID 32802887, 2020). "Surprisingly, low expression of STEAP2 was detected in breast cancer previously, consistent with the findings in this study." (PMID 32802887, 2020). "In addition, the expression of STEAP2 in breast cancer tissues and cells has been reported to be downregulated." (PMID 35346237, 2022). "STEAP2 has been reported to be downregulated in breast cancer." (PMID 35346237, 2022). "Additionally, the expression of STEAP2 also was evaluated to be a potential good predictor for patients with breast cancer." (PMID 32802887, 2020). "In breast cancer, STEAP1 and STEAP2 inhibit EMT by inhibiting EMT‐related genes and the PI3K/AKT/mTOR signaling pathway to impede cell proliferation, invasion, and metastasis." (PMID 39676279, 2024). "While STEAP3 was unrelated to any improvement in overall breast cancer patient OS, other studies have found a relationship between downregulation of the related STEAP1, STEAP2, and STEAP4 proteins and improved outcomes." (PMID 37064114, 2023). "Previous studies demonstrated that STEAP2 inhibited EMT and suppressed the PI3K–AKT–mTOR signaling pathway in breast cancer." (PMID 35436987, 2022). "Upregulation of STEAP2 can inactivate the PI3K/AKT signaling pathway and inhibit the proliferation and invasion of breast cancer cells." (PMID 35346237, 2022). "Survival analysis revealed that breast cancer patients with high levels of STEAP1, STEAP2, and STEAP4 had a good prognosis, while those with low expression had high overall mortality." (PMID 32802887, 2020). "In conclusion, through analyzing multiple databases, it is suggested that among STEAP family members, STEAP1, STEAP2, and STEAP4 have low levels in patients with breast cancer." (PMID 32802887, 2020). "STEAP1, STEAP2, and STEAP4 are predicted to be the potential prognostic biomarkers for breast cancer patients, providing novel therapeutic strategies for them." (PMID 32802887, 2020). "STEAP2 has been reported to have a reverse function in different cancers, such as a cancer-promoting effect in PRAD and a tumor-suppressive function in breast cancer." (PMID 36060273, 2022). "The results from ONCOMINE showed downregulation of STEAP1, STEAP2, and STEAP4 in breast cancers." (PMID 32802887, 2020).
breast carcinoma (continued). "Moreover, STEAP1, STEAP2, and STEAP4 are related to the prognosis of breast cancer patients, providing an important theoretical basis and clinical guidance for the development of therapeutic targets and drugs for breast cancer patients." (PMID 32802887, 2020).
papillary thyroid cancer (5 papers, 2022 to 2023). "METTL3 stabilized STEAP2 metallo reductase (STEAP2) mRNA and increased STEAP2 expression in an m6A-dependent manner in papillary thyroid cancer cells." (PMID 36835633, 2023). "In papillary thyroid cancer, METTL3 stabilizes STEAP2 RNA and positively regulates STEAP2 expression in an m6A-dependent manner, which inhibits the Hedgehog signaling pathway and suppresses cancer metastasis." (PMID 37996892, 2023). "Conversely, in a study in papillary thyroid cancer (PTC), low level of STEAP2 correlated with aggressiveness, and METTL3-mediated STEAP2 mRNA stabilization decreased PTC progression." (PMID 37369946, 2023).
ovarian carcinoma (4 papers, 2021 to 2024). A malignant neoplasm originating from the surface ovarian epithelium. "The CPTAC dataset revealed that STEAP2 total protein expression was higher in primary tissues of liver cancer, lung cancer (p < 0.001), and PAAD (p < 0.05) compared to normal tissues, but it was lower in GBM (p < 0.001) and ovarian cancer (p < 0.05) compared to normal controls." (PMID 36060273, 2022).
Ewing sarcoma (3 papers, 2021 to 2022). A small round cell tumor that lacks morphologic, immunohistochemical, and electron microscopic evidence of neuroectodermal differentiation. "Previous studies have found that STEAP1 and STEAP2 are associated with poorer patient outcomes through comprehensive microarray screening of bone marrow aspirates in Ewing’s sarcoma patients." (PMID 35346237, 2022). "STEAP2 has also been found to be overexpressed in other human cancers, including bladder, colon, pancreatic, ovarian, testicular, and cervical cancers and Ewing’s sarcoma." (PMID 35346237, 2022). "STEAP2 has also been found to be overexpressed in other human cancers, such as bladder, colon, pancreas, ovary, testis, and cervical, and Ewing’s sarcoma." (PMID 35346237, 2022). "On the contrary, it has been reported STEAP2 is overexpressed in other human cancers, e.g., bladder, pancreatic, ovarian, cervical, colon cancer, and Ewing sarcoma." (PMID 35436987, 2022).